MUC6 (mucin 6, oligomeric mucus/gel-forming (gene/pseudogene))
Diseases named in the same sentence as MUC6 in open-access papers (continued):
Sharing a sentence is not in itself a finding about the gene and the disease.
tumor (continued). "This also showed cytoplasmic or membranous expression of MUC-1, (Abcam, Ab696-250, 1:100) predominantly in the deeper aspect of the tumour, but did not stain for MUC-2 (Novocastra, NCL MUC2, 1:100), MUC5 (Novocastra, NCL MUC5, 1:100) or MUC-6 (Novocastra, NCL MUC6, 1:100)." (PMID 26589730, 2015). "The tumor in our case was negative for MUC2, MUC4, MUC5AC and MUC6." (PMID 20550696, 2010).
cancer (58 papers, 2005 to 2025). A tumor composed of atypical neoplastic, often pleomorphic cells that invade other tissues. "Subcluster M2 malignant cells were characterized by high expression levels of ANKRD3BC and MUC6, both of which were frequently mutated in cancer, and MUC6 was linked to strong immune response." (PMID 35219893, 2022). "Four of the 11 affected genes were associated with different cancer types: MUC6 and ZNF717 (prostate), SPEN (breast), and STK33 (pancreas)." (PMID 33968136, 2021). "Our findings suggest that genetic variations in MUC6 may help to predict cancer susceptibility in OSCC." (PMID 37581476, 2023). "EAC exhibits the enhanced extracellular matrix remodeling (collagens, IGFBP7, PLAU) effects expected in an aggressive form of cancer, as well as evidence of reduced expression of genes associated with mucosal (MUC6, CA2, TFF1) and xenobiotic (AKR1C2, AKR1B10) defenses." (PMID 21829465, 2011). "MUC6-positive expression reportedly signifies gastric differentiation, while negative expression correlates with the intestinal type of AoV cancer." (PMID 38893239, 2024). "Next, we analyzed the correlation between the expression levels of MUC2, MUC5AC, and MUC6 and various clinicopathological factors in the 68 patients with AoV cancer." (PMID 38893239, 2024). "MUC1, MUC2, MUC5AC, and MUC6 were the most commonly analyzed mucins across cancer types according to this literature review." (PMID 39886661, 2024). "It was shown that nine out of nineteen mucin genes (including MUC6 and MUC16) were frequently mutated in various cancer types, including HNSCC." (PMID 37504272, 2023). "MUC1, MUC2, MUC5AC and MUC6 were the most commonly analysed mucins across all three cancer types according to this literature review." (PMID 37958425, 2023). "Although many other cancer-related genes showed a high frequency of mutations in OS, the MUC family of genes (MUC6, MUC12, and MUC4) were found to be highly mutated in our study." (PMID 37046795, 2023). "We previously observed decreased αGlcNAc glycosylation of MUC6 in cancers of the pancreas, lung, common bile duct and uterine cervix." (PMID 38062108, 2023). "The importance of MUC6 in cancer is well known, but its precise role in tumorigenesis remains disputed as both oncogenic and inhibitory effects have been demonstrated." (PMID 37581476, 2023). "MUC6 expression has been observed in gastric and oncocytic phenotypes and plays an important role during cancer progression." (PMID 37581476, 2023). "MUC1, MUC2, MUC4, MUC5AC, and MUC6 are currently the most widely covered in the literature regarding their role in the progression from normal colonic tissue to cancer." (PMID 36900282, 2023). "Next, we identified prognostic gene mutations (ATR, ERBB3, KDR, and MUC6), fusions (GOPC-ROS1 and NTRK1-SH2D2A), and VEGF signaling pathway associated with cancer recurrence." (PMID 34599262, 2021). "High expression of MUC6 was associated with 100 % PFS (p = 0.024) and longer cancer-specific survival (CSS, p = 0.043)." (PMID 27298226, 2016). "For mucins with equal expression in SBC and normal tissue, MUC4 and MUC6 both showed cytoplasmic expression in carcinoma cells and normal epithelium (insets)." (PMID 24722639, 2014). "MUC2, MUC5AC, MUC5B and MUC6 genes belong to the 11p15 mucin gene cluster, which is located in a hot spot of abnormal methylation in cancer." (PMID 24281201, 2010). "Lewis y is mainly distributed at the plasma membrane of cancer cells, and carried by different glycolipids and glycoproteins, such as CD44v6, Muc6 and epidermal growth factor receptor (EGFR), which are related to carcinogenesis." (PMID 20003467, 2009). "MUC5AC and MUC6 expression were frequently observed in early carcinoma (>50%) than advanced carcinomas (>25%)." (PMID 16545139, 2006). "And in all cases, the expression of MUC1, MUC6 and 45M1 apomucins was found in the cell membranes of many carcinoma cells and the cytoplasms of some carcinoma cells." (PMID 16018800, 2005).
cancer (continued). "Therefore, we investigated the clinical significance of MUC1, MUC2, MUC5AC, and MUC6 expression in AoV cancer." (PMID 38893239, 2024). "Additionally, in GC, MUC6 expression is governed by promoter methylation, and the methylated state of the MUC6 promoter can significantly downregulate MUC6 in tumors, facilitating cancer progression." (PMID 39044262, 2024). "However, the exact role of MUC6 SNPs in cancer progression and development in Taiwanese OSCC patients remains poorly investigated." (PMID 37581476, 2023). "Most MUC6 positive cancers showed a glandular differentiation." (PMID 37057870, 2023). "Our sequencing analysis of the MUC6 fragment revealed some known mutations, confirmed also in COSMIC (Catalogue of Somatic Mutations in Cancer, version 96) and detected in different cancers." (PMID 37504272, 2023). "Published studies on MUC6 expression in cancers have reported highly variable data." (PMID 37057870, 2023). "MUC6 expression is observed in gastric and oncocytic phenotypes and may play an important role during cancer progression." (PMID 36118520, 2022). "However, Cluster 7 and Cluster 3, which were abundant in cancer-adjacent tissues, showed high expressions of Muc5ac and Muc6, respectively (markers of pit mucous cells and gland mucous cells, respectively)." (PMID 36612160, 2022). "MUC6 expression is observed in both gastric and cancer cell phenotypes." (PMID 36118520, 2022). "However, the exact role of MUC6 SNPs in cancer progression and development in Taiwanese HCC patients remains poorly investigated." (PMID 36118520, 2022). "However, when MUC6 was present in the majority of cancer cells, affected patients had an excellent prognosis." (PMID 27298226, 2016). "It has been suggested that overexpression of MUC6 mucin domains inhibits invasion of cancer cells in vitro, whereas in some cases the expression of this secreted mucin seems to correlate with the degree of histopathology, which is related to malignant potential." (PMID 23056409, 2012). "MUC5AC and MUC6 expressions were decreased in advanced carcinomas (>25%)." (PMID 16545139, 2006). "Two cases of superficially invasive carcinomas showed surface predominant MUC5AC expression and deep layer MUC6 expression, similar expression to that seen in normal gastric mucosa." (PMID 39164422, 2025). "AoV cancer typically exhibits a desmoplastic stroma and commonly expresses MUC1, MUC5AC, MUC6, and MUC2." (PMID 38893239, 2024). "For example, several well-known cancer driver genes exhibit higher frequencies of alterations in normal organs compared to cancers, like NOTCH, ERBB, and MUC6." (PMID 39883325, 2024). "KMT2D and GATA3 were uniquely identified in African Americans as cancer drivers reported in TCGA data, whereas PIK3CA, MAP3K1, CDH1, and MUC6 were identified in Caucasians." (PMID 37454130, 2023). "In the current study, we selected three MUC6 SNPs (rs61869016 (5'-UTR), rs6597947 (5'-UTR), and rs7481521 (exon)) with the aim of elucidating their correlations to Taiwanese HCC patients and cancer prognosis." (PMID 36118520, 2022). "The expression rates in cancer lesions (more than 5% of carcinoma cells stained) were MUC1, 51.7% (31/60); MUC2, 26.7% (16/60); MUC3, 55% (33/60); MUC4, 51.7% (31/60); MUC5AC, 33.3% (20/60); MUC6, 10% (6/60) and MUC16, 8.3% (5/60)." (PMID 24722639, 2014). "Immunoreactivities to Ki-67, EMMPRIN, and VEGF were weaker in IT carcinoma than in the MT intestinal portion (p < 0.05), while the opposite was true for CD44, MUC-2, and MUC-6 (p < 0.05)." (PMID 18266006, 2008).
cancer (continued). "Immunoreactivities to Ki-67, EMMPRIN, and VEGF were weaker in the intestinal-type carcinomas than in the intestinal component of the MT (p < 0.05), while it was the opposite for CD44, MUC-2, and MUC-6 (p < 0.05)." (PMID 18266006, 2008). "The existence of sizable subgroups of MUC6 positive and negative tumors within many clinically relevant cancer types raises the question of a possible prognostic or predictive role of MUC6 expression." (PMID 37057870, 2023). "Akin to MUC5AC, MUC6 expression decreased with cancer formation in the esophagus but not in the stomach." (PMID 36994101, 2023). "In our present case, Brunner’s gland adenocarcinoma was indicated by the fact that the cancer was surrounded by Brunner’s gland hyperplasia and immunostaining analysis was positive for MUC6 and negative for MUC5AC." (PMID 31728658, 2019). "Surprisingly, patients with MUC3A, MUC4, MUC5B, MUC6, and MUC16 mutations had significantly better OS prognoses compared with those without mutations in several cancer types." (PMID 30107644, 2018). "In this study, we investigated the relationships between mucin expression and clinicopathologic factors in 60 SBC cases, in which expression profiles of MUC1, MUC2, MUC3, MUC4, MUC5AC, MUC6 and MUC16 in cancer and normal tissues were examined by immunohistochemistry." (PMID 24722639, 2014). "On the other hand, no carcinoma cells in all SMCa lesions were positive for MUC6, although the pyloric glands and the remnant pyloric glands in SMCa lesions, which were seen in the same slides, were positive for MUC6." (PMID 16135257, 2005). "On the other hand, no positive carcinoma cells for MUC6 were seen although the pyloric glands and the remnant pyloric gland in the SMCa lesions in the same slides were positive for MUC6." (PMID 16135257, 2005). "Therefore, the current study aims to investigate the correlations between three MUC6 SNPs (rs61869016, located in the 5′‐UTR; rs6597947, located in the 5′‐UTR and rs7481521, located in the exon) and Taiwanese male patients with OSCC and their cancer prognosis." (PMID 37581476, 2023). "In the 108 cases, the positive expression rates (more than 5% of carcinoma cells stained) of each mucin antigen were MUC1, 47.2% (51/108); MUC2, 71.3% (77/108); MUC3, 18.5% (20/108); MUC4, 93.5% (101/108); MUC5AC, 50.0% (54/108); MUC6, 4.6% (5/108) MUC16, 16.7% (18/108) and MUC17, 86.1% (93/108)." (PMID 25551773, 2014). "In Case 1, the dysplastic and carcinoma cells were strongly positive for CK7, MUC1, and MUC6 but negative or only focally positive for CK20, MUC2, CDX2, and MUC5AC." (PMID 27656307, 2016). "In Case 2, the neoplastic and carcinoma cells were strongly positive for MUC5AC and MUC6 but only focally positive or negative for MUC1, MUC2, CDX2, CK7, and CK20, suggesting that this immunophenotype was compatible with the gastric type." (PMID 27656307, 2016). "Unlike the less consistent expression patterns of MUC1, MUC6 and MUC5AC in normal and cancer tissues, MUC2 levels were always measured low in normal endometrial and cervical tissue, and elevated MUC2 expressions were specifically found in various neoplastic lesions." (PMID 22417007, 2012).
adenocarcinoma (11 papers, 2005 to 2025). A common cancer characterized by the presence of malignant glandular cells. "EBVaGCs with intestinal histology were frequently accompanied by genetic alterations, which were known to frequently occur in conventional intestinal-type adenocarcinoma, including KRAS, FBXW7, MUC6, ERBB2, CTNNB1, and ERBB2 amplification mutations." (PMID 37945587, 2023). "One adenocarcinoma sample consisted of MUC6-positive atypical cells growing in a glandular pattern." (PMID 40463821, 2025). "A total of four studies looked specifically at the adenocarcinoma of the oesophago-gastric junction (GOJc), analysing MUC1, MUC2, MUC5AC and MUC6 in 191 surgically resected specimens." (PMID 37958425, 2023). "Intestinal-type adenocarcinomas generally express CDX-2, MUC2 and CD10, whereas the gastric-type adenocarcinomas express MUC5AC and MUC6." (PMID 35565398, 2022). "Here, we sought to characterize the expression profile of SOX2 and CDX2 in the sequential alterations of the esophageal mucosa towards adenocarcinoma and compare it with the well-established gastric and intestinal mucin profiles (MUC5AC, MUC6, and MUC2)." (PMID 27766003, 2016). "In conclusion, decreased αGlcNAc glycosylation on the MUC6 scaffold protein also decreases TFF2 levels in that complex and could serve as an indicator of relatively high-grade PGA progressing to adenocarcinoma." (PMID 38062108, 2023).
infection (10 papers, 2010 to 2024). The state of being infected such as from the introduction of a foreign agent such as serum, vaccine, antigenic substance or organism. "Among the membrane bound and secreted mucins tested, MUC1, MUC20 and MUC6 transcription levels were observed to increase during the infection." (PMID 21569362, 2011). "In addition, the expression of MUC6 is increased; considering the antibiotic effect of the mucin, this is likely a defense mechanism of the stomach against infection." (PMID 33322136, 2020). "For example, spermatozoa and Semen Derived Enhancer of Virus Infection (SEVI, small aggregates or fibrils) can bind HIV-1 and promote infection of target cells, whilst semenogelin-I inhibits direct infection of target cells and MUC6 and clusterin interfere with DC-SIGN mediated trans-infection." (PMID 25793526, 2015). "Given that MUC1 from human milk and MUC6 from seminal plasma are known to inhibit DC-SIGN mediated HIV-1 trans-infection one might have expected another member of this family to be expressed in CM and binding DC-SIGN." (PMID 25793526, 2015). "However, we did see a modest up-regulation of Muc6 mRNA expression during infection of WT mice, and the impact of this expression is currently under investigation." (PMID 20485566, 2010). "There were no major changes in any of these mucins except for Muc6, which was elevated in Muc2−/− mice at baseline and also increased in WT mice during infection relative to uninfected WT controls." (PMID 20485566, 2010). "As concluded by a meta-analysis that included 11 case-control studies, comparing human gastric mucin expression using immunohistochemistry in H.pylori positive and negative patients, the infection causes decreased MUC5AC expression and increased MUC6 expression." (PMID 33322136, 2020). "Similarly to the mucus changes during different time points of infection in WT animals, Muc1, Muc2, Muc4 or Muc6 mRNA levels did not explain the differences in mucus thickness between IFN-γ−/- and WT mice." (PMID 30665337, 2019). "Increased gene expression of MUC1, MUC6 and MUC20 was observed, while MUC5AC did not change during infection." (PMID 21569362, 2011).
respiratory disease (1 paper, 2022). "Type II gastric mucin contains mucin 2 and mucin 6 (MUC2/MUC6), as well MUC5AC, and although these are not the major secreted mucins in saliva, they are gel-forming and serve as a surrogate for the secretory gel-forming mucins in saliva upregulated during respiratory disease." (PMID 36146663, 2022).
MUC6 also shares sentences with these, for which no sentence is quoted: cervical cancer (3 papers); tubular adenocarcinoma (3); Barrett’s esophagus (2); colorectal adenocarcinoma (2); diabetes (2); gastrointestinal tumor (2); Obesity (2); osteosarcoma (2); ovarian carcinoma (2); pancreatic adenocarcinoma (2); acute myeloid leukemia (1); Allergy (1); asthma (1); autoimmune disease (1); bronchiectasis (1); bronchioalveolar carcinoma (1); bronchiolitis (1); cholelithiasis (1); chronic bronchitis (1); co-infection (1); colon adenocarcinoma (1); colonic polyps (1); cystic papillary neoplasm (1); diabetes retinopathy (1); diverticulosis (1); duodenal neoplasm (1); duodenal ulcer (1); endometrial cancer (1); endometrioid endometrium carcinoma (1); endometrioid ovarian carcinomas (1).
A further 39 diseases each share a sentence with MUC6 in 1 paper.